TNF (tumor necrosis factor)
Diseases named in the same sentence as TNF in open-access papers (continued):
Sharing a sentence is not in itself a finding about the gene and the disease.
rheumatoid arthritis (continued). "The migration of CD16+ monocytes to tissues and the inflammatory responses they mediate, including the production of TNF-α and ROS, have the potential to aggravate autoimmune diseases such as lupus nephritis and rheumatoid arthritis." (PMID 36059489, 2022). "TNF inhibitors are used to treat autoimmune conditions such as rheumatoid arthritis, juvenile arthritis, psoriatic arthritis, transplant recipients, and inflammatory bowel disease." (PMID 36159650, 2022). "The presented study aimed to compare the real-world data on treatment retention in ATTRA (Anti-TNF Treatment in Rheumatoid Arthritis) registry patients receiving first-line treatment with a TNFi combined with csDMARDs and in those treated with a TNFi alone." (PMID 35338383, 2022). "Combination therapy with a TNF-α inhibitor and an oral immunomodulator is often utilized for patients with rheumatoid arthritis or IBD to enhance the efficacy of the biologic drug, or reduce the risk of immunogenicity." (PMID 35409118, 2022). "Several inflammatory cytokines from the synovial tissue in rheumatoid arthritis, such as tumor necrosis factor-α (TNF-α) and IL-6 trigger an increased expression of RANKL and matrix metaloproteinases (MMPs)." (PMID 35160258, 2022). "Infliximab, a chimeric anti-TNFα monoclonal antibody, has been demonstrated to be an effective therapy for rheumatoid arthritis, Crohn's disease, ankylosing spondylitis and other autoimmune diseases." (PMID 35177742, 2022). "For example, the inhibition of neuroinflammatory cytokines (such as TNF or cyclooxygenase 2) has been shown to have significant antidepressant effects in depressive patients with rheumatoid arthritis, psoriasis, or cancer." (PMID 36186850, 2022). "The results showed that inhibition of autophagy can improve the imbalance of proliferation / apoptosis of fibroblast like synoviocytes aggravated by TNF – α to a certain extent, thus delaying the degree of rheumatoid arthritis." (PMID 35232381, 2022). "Overexpression of TNF-a in lung epithelial cells is also an important factor in the secondary interstitial pneumonia of rheumatoid arthritis." (PMID 35600883, 2022). "The present study evaluated the predictive role of baseline radiographic change and disease activity on drug retention and clinical response in patients with rheumatoid arthritis (RA) treated with tumor necrosis factor inhibitor (TNFi)." (PMID 36402804, 2022). "For example, treating rheumatoid arthritis with tumor necrosis factor (TNF) antagonists lowers the incidence of Alzheimer’s disease and type II diabetes." (PMID 36313344, 2022). "KEGG pathway analysis showed that NFIL3-related genes were involved in the IL-17 signaling pathway, rheumatoid arthritis pathway, and TNF signaling pathway." (PMID 36439145, 2022). "Most significant enriched pathways in all three infection conditions belonged to the immune system category, including TNF and IL-17 signaling, Rheumatoid arthritis, and cytokine–cytokine receptor interaction." (PMID 35638758, 2022). "Anti-tumor necrosis factor (TNF) α autoantibody is effective in the treatment of rheumatoid arthritis, Graves’ disease, psoriasis and inflammatory bowel disease." (PMID 36341384, 2022). "Tumor necrosis factor-α (TNF-α) lies at the apex of signal transduction cascades that results in induced destruction of joints in rheumatoid arthritis." (PMID 35340587, 2022). "Therapeutics targeting tumor necrosis factor-α (TNF-α) and interleukin (IL) 1 and 6 are used to treat rheumatoid arthritis (RA), inflammatory bowel disease (IBD), and psoriasis." (PMID 35565972, 2022). "The top 10 keywords were “rheumatoid-arthritis”, “expression”, “inflammation”, “macrophages”, “activation”, “collagen-induced arthritis”, “NF-κB”, “cytokines”, “TNF-α”and “T cell”." (PMID 36172378, 2022).
rheumatoid arthritis (continued). "It is known that tumor necrosis factor alpha (TNF-α) is present in the synovial fluid of patients with rheumatoid arthritis and induces the expression of proinflammatory cytokines in synovial cells." (PMID 36235230, 2022). "TNF-α blockers, or anti-TNF-α (aTNF-α), have been involved in the treatment of psoriasis vulgaris, rheumatoid arthritis, and inflammatory bowel disease and were recently approved for hidradenitis suppurativa." (PMID 36685489, 2022). "The same protective effect is observed in a murine model of rheumatoid arthritis where a preestablished Schistosoma infection causes a downregulation of the level of anticollagen IgG, IFN-γ, IL-17A, TNF-α, IL-1β, and IL-6 and an upregulation of IL-4." (PMID 35113966, 2022). "TNF-α inhibitors are already successfully used in the treatment of Chron’s disease or rheumatoid arthritis." (PMID 36267276, 2022). "In rheumatoid arthritis (RA), biologic DMARDs (bDMARDs), especially TNF inhibitors, decrease the risk of hospitalization, while rituximab and systemic corticosteroids increase the hospitalization risk; thus, the risk of severe COVID-19 infection also depends largely on treatment modalities." (PMID 36293117, 2022). "For example, in a study of rheumatoid arthritis, Derinat® was found to suppress tumor necrosis factor alpha (TNF-α) and accelerate blast transformation of lymphocytes in rats." (PMID 36642990, 2022). "For example, low yet persistent TNF expression was revealed to induce rheumatoid arthritis as well as inflammatory bowel diseases (IBDs)." (PMID 35422450, 2022). "These genes were mainly enriched in the IL-17 signaling pathway, TNF signaling pathway, and rheumatoid arthritis pathways." (PMID 36439145, 2022). "The TNFα inhibitors have been commonly used to treat diverse inflammatory diseases such as inflammatory bowel disease, rheumatoid arthritis (RA), psoriasis, psoriatic arthritis, and heart failure." (PMID 36497082, 2022). "YBLI of 8 weeks has significantly reduced the expression of TNF-α and IL-6 genes in rheumatoid arthritis patients." (PMID 36004368, 2022). "Firstly, TNF-α stimulated human rheumatoid arthritis fibroblast-like synoviocyte MH7A cells were applied to test the effects of pristimerin on proliferation and migration using MTT and transwell assays." (PMID 36144243, 2022). "IL-1β, IL-6, IL-8, and TNF-α are involved in the pathogenesis of many inflammatory diseases including rheumatoid arthritis, psoriatic arthritis, and IBD." (PMID 36505430, 2022). "On the other hand, we know that TNFα inhibitors are successfully used in the treatment of arthritis in the course of other diseases, e.g., rheumatoid arthritis, and joint symptoms are one of the more common symptoms in the course of pSS." (PMID 36143051, 2022). "Earlier studies in patients with psoriasis or rheumatoid arthritis pointed to a lower incidence of hard cardiovascular endpoints with TNF-α inhibitors." (PMID 36555579, 2022). "As a pro-inflammatory cytokine, TNF-α is central to the inflammatory process of autoimmune diseases such as rheumatoid arthritis (RA)." (PMID 36060429, 2022). "The rationale for a possible use of anti-TNFα in COVID-19 stems from clinical studies in rheumatoid arthritis." (PMID 36579506, 2022). "There are FDA licensed anti-TNF-α antibody therapeutics currently marketed for treating automimmune disorders such as rheumatoid arthritis." (PMID 35587473, 2022). "In the published article, NF-κB is an inducer of miR-18a in TNFα-induced rheumatoid arthritis synovial fibroblasts." (PMID 35148687, 2022). "IL-1β and TNFα are pro-inflammatory cytokines that are expressed in common chronic pathologies such as rheumatoid arthritis, diabetes, myocardial infarction, and inflammatory lung diseases." (PMID 36101361, 2022). "Consistently, SHBG levels rebounded in patients with chronic inflammatory states, such as rheumatoid arthritis, using a TNF-α inhibitor." (PMID 35493382, 2022).
rheumatoid arthritis (continued). "Several monoclonal antibody‐based therapeutics have been approved targeting TNF‐α to control inflammation in inflammatory diseases like rheumatoid arthritis and Crohn's disease." (PMID 35811493, 2022). "It has been shown that trough levels of anti-TNFα agents reflect the efficacy in rheumatoid arthritis and in CD." (PMID 35346067, 2022). "TNF-α is involved in the development and exacerbation of autoimmune and inflammatory diseases such as rheumatoid arthritis." (PMID 35200250, 2022). "Since pro- and anti-inflammatory cytokines play a key role in the pathogenesis and evolution of the inflammatory state of rheumatoid arthritis, three typical markers of rheumatoid arthritis were monitored: IL-1β, IL-6, and TNF-α." (PMID 36421448, 2022). "When human rheumatoid arthritis synovial fibroblasts were transfected with Cx43 siRNA, the upregulation of TNF-α and IL-6 gene expression induced by TNF-α was significantly inhibited." (PMID 36465186, 2022). "KEGG changes were mainly enriched in several immune system diseases (e.g., leishmaniasis and rheumatoid arthritis) and immune-related pathways (e.g., TNF signalling pathway, interleukin (IL-17) signalling pathway, and NF-κB signalling pathway)." (PMID 35419117, 2022). "The most likely connection between type 2 diabetes and rheumatoid arthritis involves inflammation and the accumulation of cytokines such as tumor necrosis factor (TNF)." (PMID 36234810, 2022). "Interestingly, patients with rheumatoid arthritis (RA) and psoriasis were reported with a low risk of developing AD when treated with TNF blockers therapy (i.e., etanercept, adalimumab, and infliximab), which suggests that blocking TNF expression may have a neuroprotective effect against AD." (PMID 35651608, 2022). "KEGG pathway analyses revealed that pathways were significantly enriched including IL-17 signal path, rheumatoid arthritis, TNF signal path, and lipid and atherosclerosis." (PMID 35733917, 2022). "In humans, erythema multiforme with characteristic skin lesions was observed following anti-tumor necrosis factor (TNF)-α medication with adalimumab for rheumatoid arthritis or after exposure to different herbicides." (PMID 35336226, 2022). "For instance, an opportunistic infection has been reported when TNF‐α was neutralized for rheumatoid arthritis therapy." (PMID 34626163, 2022). "In rheumatoid arthritis, an autoimmune disease, MCs participate in the production and activation of the cytokines TNF and IL-6." (PMID 36362030, 2022). "TNFα is involved in the development of inflammatory diseases such as atherosclerosis, rheumatoid arthritis, and various pulmonary disorders." (PMID 35741013, 2022). "A 12-year persistence and male gender are both predictors of failure of the initial biologic therapy in patients with rheumatoid arthritis and psoriatic arthritis, while a lower efficacy of anti-TNF drugs is observed in females with axial spondyloarthritis." (PMID 35203537, 2022). "The approved therapeutic use of anti-TNF monoclonal antibodies is currently limited to autoimmune diseases, such as rheumatoid arthritis, Chron’s disease, or psoriatic arthritis." (PMID 35328704, 2022). "In case study 1, EFA was used to predict the effective dose of two well-studied anti-TNFα agents: adalimumab and infliximab for the treatment of rheumatoid arthritis (RA)." (PMID 35754500, 2022). "TNF-alpha inhibitors have an important role in the treatment of chronic systemic immune-mediated conditions such as rheumatoid arthritis, ankylosing spondylitis, psoriatic arthritis and inflammatory bowel diseases." (PMID 36703896, 2022). "Excessive production of TNF-α by macrophages can also lead to serious pathological conditions such as septic shock and rheumatoid arthritis." (PMID 35330323, 2022). "Uncontrolled TNF-TNFR signaling is associated with the pathogenesis of many diseases, including immune-mediated inflammatory disorders (IMIDs) such as SpA, rheumatoid arthritis, and inflammatory bowel disease." (PMID 35216345, 2022).
rheumatoid arthritis (continued). "It seems like inflammatory genes were not responding as they were intended to like in another similar study, in which 8 weeks of yoga-based lifestyle intervention significantly decreased the TNF-α and IL-6 expression in patients with rheumatoid arthritis." (PMID 36004368, 2022). "Overexpression of miR-125b induces the expression of TNF-α, IL-6 and IL-1β in plasma from rheumatoid arthritis patients, showing a strong positive correlation between miR-125b and TNF-α." (PMID 36668754, 2022). "KEGG analysis showed that hub genes were significantly enriched in the IL-17 signaling pathway, lipid and atherosclerosis, rheumatoid arthritis and TNF signaling pathway." (PMID 35397550, 2022). "Baricitinib is a synthetic inhibitor of the isoforms JAK1/JAK2; this drug shows few drug–drug interactions and is currently used in rheumatoid arthritis when the anti-TNF therapy fails." (PMID 35631442, 2022). "KEGG pathway analysis indicated that the DEGs were significantly enriched in Cytokine-cytokine receptor interaction, IL-17 signaling pathway, Rheumatoid arthritis and TNF signaling pathway." (PMID 36118873, 2022). "MiR-18a-5p increased the expression of MMP1, inflammatory cytokines and chemoattractant proteins in rheumatoid arthritis synovial fibroblasts through NF-κB dependent manner after TNFα stimulation." (PMID 35148687, 2022). "TNFα has a crucial function in chronic inflammatory diseases such as rheumatoid arthritis, inflammatory bowel disease, and atherosclerosis." (PMID 36279189, 2022). "For example, in 75 patients starting anti-TNF therapy for rheumatoid arthritis or spondyloarthropathies, three patients who developed neurological symptoms demonstrated new cortical lesions consistent with demyelination on MRI6." (PMID 35694196, 2022). "It was shown that serum Cu level in rheumatoid arthritis patients was elevated and the Cu level in RA patients was positively correlated to IL-1β and tumor necrosis factor-α (TNF-α)." (PMID 35070279, 2022). "Although inflammation has been directly linked to the development of LV diastolic dysfunction in patients with rheumatoid arthritis, the effects of tumor necrosis factor alpha (TNF-α) inhibitors on LV diastolic dysfunction and HFpEF have been contradictory." (PMID 36494772, 2022). "Specifically, B cell responses were reduced in response to the anti-TNFα treatment in patients with rheumatoid arthritis, following the seasonal influenza vaccination." (PMID 35893835, 2022). "Reports show that the effect of TNF α on inflammatory mechanisms in rheumatoid nodules is less effective compared to joints, so treatment with TNF α inhibitors cannot treat pulmonary nodules." (PMID 36422501, 2022). "sTNF-R has already been clinically applied as a specific medicine to regulate the action of TNF-α during the inflammatory response in rheumatoid arthritis." (PMID 35200250, 2022). "Infliximab and Tocilizumab are TNF-α and interleukin (IL)-6 inhibitors, respectively, and are currently prescribed to treat rheumatoid arthritis." (PMID 36077532, 2022). "Reduced responses after hepatitis A are also described in patients with other diseases such as rheumatoid arthritis on anti-TNF therapy." (PMID 35629116, 2022). "In patients with rheumatoid arthritis and CKD, the administration of anti-TNF-α was associated with less renal function decline." (PMID 35328704, 2022). "Meanwhile, disease-modifying anti-rheumatoid drugs (DMARD), steroids (dexamethasone), and biologic DMARDs (anti-tumor necrosis factor–α; anti-TNF-α) are used for rheumatoid arthritis." (PMID 36429168, 2022). "KEGG enrichment analysis revealed that the genes in this gene cluster were mainly involved in the IL-17 signaling pathway, lipid and atherosclerosis, rheumatoid arthritis, and TNF signaling pathway." (PMID 35397550, 2022).
rheumatoid arthritis (continued). "For example, only 0.2% of the patients treated with anti-TNF for rheumatoid arthritis were diagnosed with tuberculosis after treatment, and in a prospective study from Japan that followed 570 patients for 1 year, no case of active tuberculosis was observed." (PMID 35140875, 2022). "Findings that excess TNF promotes inflammation led to the development of TNF inhibition as a first-line biologic therapy for many autoimmune diseases, including rheumatoid arthritis, psoriasis, and inflammatory bowel disease." (PMID 35104241, 2022). "It is, thus, not surprising that the variant rs2233945, localized in the same PSORS1C1 gene, modulates the response to etanercept, a TNF inhibitor used for psoriasis and other autoimmune disorders, including rheumatoid arthritis." (PMID 36077453, 2022). "We also found that monocytes, especially cluster 6 (classical monocytes) from patients with COPD, were enriched in NF-κB signalling pathway, TNF signalling pathway, and rheumatoid arthritis." (PMID 36127695, 2022). "Meanwhile, KEGG assays revealed that pathways were significantly enriched including IL-17 signal path, rheumatoid arthritis, TNF signal path, and lipid and atherosclerosis." (PMID 35733917, 2022). "Similar to the targeting of IL-6, anti-TNFα mAbs are used to treat inflammatory conditions, such as rheumatoid arthritis, juvenile arthritis, inflammatory bowel diseases, and psoriasis (reviewed in Refs." (PMID 35890077, 2022). "In a murine rheumatoid arthritis model, AS-IV was shown to inhibit the expression of nitric oxide (NO), tumor necrosis factor-α (TNFα), and interleukin-1β (IL-1β)." (PMID 35877777, 2022). "Cytokines produced from many synovial cell groups are the core of the pathogenesis of rheumatoid arthritis, including a variety of cytokines TNF-α, IL-1 family, and IL-6." (PMID 35600883, 2022). "It is well known that IL-6 and TNF-α are confirmed to mediate many chronic inflammatory diseases, especially rheumatoid arthritis." (PMID 36578485, 2022). "Although approved by the Food & Drug Administration (FDA) for some patients with rheumatoid arthritis, Anakinra is only moderately effective and is inferior to TNF-α inhibitors, indicating its poor applicability." (PMID 35833125, 2022). "TNF-α inhibitors, which are antibodies that lower inflammation in both atherosclerosis and autoimmune illnesses like rheumatoid arthritis, include infliximab, etanercept, and adalimumab." (PMID 36703734, 2022). "Tumor necrosis factor alpha (TNF-alpha) inhibitors are a class of biotherapies that has revolutionized the therapeutic care in chronic inflammatory diseases, such as psoriasis, rheumatoid arthritis and Crohn’s disease." (PMID 36380105, 2022). "An association between MS and rheumatologic diseases, in particular rheumatoid arthritis, has been described and numerous studies acknowledge anti-TNF-α drugs as MS triggers." (PMID 36009588, 2022). "It is suggested that TNF-TG mice can be used as a stable model for cardiopulmonary complications of rheumatoid arthritis in the study of RA complications." (PMID 35600883, 2022). "The reads were analyzed using KEGG pathway analysis, which revealed enrichment in rheumatoid arthritis and several inflammatory pathways in TNF-α-stimulated FLSs." (PMID 35982301, 2022). "The use of TNFα inhibitors, such as infliximab, has been shown to reduce osteoclastic bone resorption in rheumatoid arthritis." (PMID 36013064, 2022). "Functional annotation analyses showed that the identified DEGs were associated with rheumatoid arthritis, the regulation of the ERK1/2 cascade, ECM-receptor interactions, the regulation of inflammatory response, and the TNF signaling pathway." (PMID 35164658, 2022). "Activation of angiotensin type II-angiotensin type I receptor further stimulates TNF-α and soluble IL-6 rheumatoid arthritis form." (PMID 35178309, 2022).